IL18 (interleukin 18)
Diseases named in the same sentence as IL18 in open-access papers (continued):
Sharing a sentence is not in itself a finding about the gene and the disease.
Sepsis (continued). "Experimental data suggest that secretion of HMGB1 and several inflammatory cytokines (e.g. IL-18) in severe sepsis is inflammasome-dependent." (PMID 27434276, 2016). "Accumulating evidences indicate the therapeutic effects of neutralizing anti-IL-18 antibody and IL-18 binding protein (IL-18BP) in various autoimmune diseases, inflammatory bowel disease, sepsis, and acute kidney injury." (PMID 27888626, 2016). "The phylum Firmicutes and the families Streptococcaceae and Lactobacillaceae were negatively correlated with many inflammatory markers of sepsis progression, such as IL-6, IL-18, HMGB1 and CRP." (PMID 25881250, 2015). "There are also some biomarkers such as IL-1 and IL-18, that show the predictive value of sepsis post-trauma, but the studies are few and the results need further evidence to support this." (PMID 27602370, 2014). "While IL-18 is detectable in healthy human subjects, levels exhibited by critically ill patients with sepsis are nearly 10-fold higher." (PMID 24555158, 2013). "IL-18 itself has previously been reported to be upregulated during sepsis and given its genomic location adjacent to IL18RAP, is likely to be co-ordinately regulated." (PMID 24146790, 2013). "Critically ill patients with sepsis exhibited significantly higher levels of IL-18 compared with healthy subjects administered small doses of endotoxin." (PMID 24555158, 2013). "Overproduction of proinflammatory cytokines (e.g. TNF-α, IL-12, IFN-γ and IL-18) results in sustained sepsis, shock, and even death." (PMID 21194488, 2011). "However, in mice undergoing cecal ligation and puncture‐induced polymicrobial sepsis or E. coli‐induced sepsis, NLRP6‐mediated release of IL‐18 exacerbates sepsis." (PMID 39351983, 2025). "A deeper understanding of this mechanism may inform the development of precision therapies targeting key cytokines—such as IL-1β and IL-18—or downstream effectors to mitigate cytokine storms in severe AOSC patients with sepsis and reduce mortality." (PMID 41438472, 2025). "Our primary objective was to evaluate IL-18 as a diagnostic biomarker for differentiating abdominal from non-abdominal sepsis." (PMID 40510342, 2025). "Notably, clopidogrel has recently demonstrated efficacy in suppressing platelet inflammasome activation, thereby reducing the release of IL-1β and IL-18 and improving renal outcomes in sepsis models." (PMID 40692784, 2025). "From a biological standpoint, IL-18 is a highly plausible candidate as a sepsis biomarker." (PMID 40510342, 2025). "Some data suggest that IL-18 may help differentiate sepsis origins, offering a path toward source-specific diagnosis." (PMID 40510342, 2025). "Studies analyzing proinflammatory cytokines, such as IL-8, IL-12, IL-17A, and IL-18, and anti-inflammatory cytokines, such as IL-4, IL-10, and IL-11, have reported no effective neutralizing antibodies to improve the outcomes of human sepsis." (PMID 40136690, 2025). "Moreover, sepsis induction leads to the generation of proinflammatory cytokines such as IL-1β, IL-18, and TNF-α." (PMID 40770673, 2025). "Finally, we evaluated the mechanisms by which IL-18 enhances mortality in NLRP6 KO mice following sepsis." (PMID 38720893, 2024). "Furthermore, NLRP6 plays a detrimental role in host defense during sepsis through IL-18-mediated destructive inflammation." (PMID 38720893, 2024). "In addition, Pearson correlation analysis showed a positive correlation between circMAPK1 and IL-1β/IL-18 levels in patients with sepsis-induced lung injury, suggesting the potential role of circMAPK1 in modulating inflammation in sepsis-induced lung injury." (PMID 39300342, 2024). "In addition, we have shown that NLRP6-driven IL-18 enhances mortality in sepsis through mediating both inflammation and cell death." (PMID 38720893, 2024). "It is speculated that this may be related to the involvement of NLRP3 and IL‐18 in the process of sepsis." (PMID 39692606, 2024).
Sepsis (continued). "IL-18 administration reversed the survival advantage observed in the KO mice following sepsis." (PMID 38720893, 2024). "Once activated, IL-18 promotes further inflammation and tissue damage, particularly in organs like the lungs and kidneys, which are already compromised during the acute phase of sepsis." (PMID 39594987, 2024). "Our results indicated that Daph treatment improved survival rate and alleviated pulmonary pathological damage of the sepsis mice, as well as reduced the excessive release of pro-inflammatory cytokines IL-1β, IL-18, IL-6, iNOS and chemokines MCP-1 regulated by MAPK/NF-κB pathway in pulmonary injury." (PMID 36998049, 2023). "Inflammasome activation plays a vital role in hyperinflammation during sepsis, as it triggers the production and release of proinflammatory cytokines, such as IL-1β (Interleukin 1β) and IL-18 (Interleukin 18), and induces inflammatory cellular death, including pyroptosis and necroptosis." (PMID 37711629, 2023). "During pyroptosis, IL-1β and IL-18, both important inflammatory cytokines in sepsis, are released." (PMID 36756123, 2023). "Additionally, we found that elevated soluble P2X7 receptor in plasma correlated with the inflammasome-dependent release of IL-18 in sepsis." (PMID 38094297, 2023). "However, there was a trend in the median values between the three groups in the concentrations of IL-18 and sCD163: the lowest values were observed in the control group, the intermediate values in sepsis, and the highest values in septic shock." (PMID 36767629, 2023). "Multivariate analysis included urine Ba, urine IL-18, urine NGAL, sepsis, and Pediatric Risk of Mortality Scores-II (an estimate of illness severity) and showed a significant association between urine Ba and AKI (odds ratio 1.57, 95% confidence interval, 1.13 to 2.20; P 0.007)." (PMID 36758197, 2023). "In human studies using plasma specimens from critically ill patients, the expression of inflammasome-related caspase 1, IL-18 and IL-1β mRNA transcripts was significantly higher in patients with sepsis or ARDS, compared with patients with systemic inflammatory response syndrome alone." (PMID 36232959, 2022). "In addition to causing lymphopenia, sepsis impairs NK cell cytotoxicity and IFN-γ responses to IL-18." (PMID 35190900, 2022). "While IL-18 neutralizing mAb has been suggested for the treatment of various autoimmune and autoinflammatory diseases by experimental studies and clinical trials, its role in sepsis is less clear." (PMID 35203474, 2022). "Serum levels of urea and creatinine are influenced by other factors (especially in sepsis) and, hence, the evaluation of further biomarkers, such as IL-18 and kidney injury molecule-1 which are markers that have been found to be upregulated early after renal insult in sepsis." (PMID 35774785, 2022). "In addition to LIGHT, interleukin-18 (IL-18) has been repeatedly highlighted as a major player in sepsis." (PMID 35203474, 2022). "Wild-type mice, as well as IL-18(−/−) mice were resistant to sepsis." (PMID 35563475, 2022). "Moreover, among sepsis patients, those who died had notably elevated cytokines, IL-1β, IL-18, and chemokines, MIP-3α, ENA-78, relative to survivors." (PMID 35291488, 2022). "The lack of correlation between LIGHT and IL-18 levels, as well as different correlations with other biomarkers, suggests independent and distinct roles of LIGHT and IL-18 in sepsis, and that therapy directed against both of these cytokines should be given consideration." (PMID 35203474, 2022). "Despite these limitations, these results could help to generate new hypotheses on the prognostic, but also etiological, role of IL-6 and IL-18 in sepsis." (PMID 36189302, 2022). "Early in sepsis, Kupffer cells play an essential role in the removal of bacteria and endotoxins through the release of proinflammatory cytokines such as interleukin (IL)-1β, IL-6, IL-18, and tumor necrosis factor-alpha (TNF-α)." (PMID 36120368, 2022).
Sepsis (continued). "In a previous proteomics study conducted by our group in adult sepsis patients, we proposed a set of 10 proteins (AT-III, CLUS, SAA-1, HO-1, IL-6, IL-18, sCD25, sCD163, sICAM-1 and sFas) that can be considered as a complementary tool for the clinicians in the diagnosis of sepsis." (PMID 35329889, 2022). "In line with this, the experimental results from ELISA analysis underlined that sepsis might lead to inflammatory response by elevating the levels of TNF-α, IL-6, IL-1β and IL-18." (PMID 35264055, 2022). "In addition, the activation of the IL-17signaling pathway augments pyroptosis with GSDMD cleave and IL-1 1β and IL-18 release in pneumonia-induced sepsis." (PMID 36457716, 2022). "Experimental data show that biological neutralization of IL-18 may be a promising therapeutic approach in the treatment of sepsis; however, further studies will be needed to assess their full potential in the treatment of sepsis in humans." (PMID 34577795, 2021). "Although the possible role of IL-18 in facilitating dengue disease progression remains undefined, altered IL-18 production has been reported in various inflammatory conditions, for example, in sepsis, diabetes, metabolic syndromes, atherosclerosis, and cardiovascular disorders." (PMID 34734091, 2021). "It is suggested that IL-18 could be used as a biomarker of monitoring sepsis severity throughout recovery in critically ill patients." (PMID 35054259, 2021). "Unfortunately, due to the small sample size of septic patients in our study, a cut-off value of IL-18/IL-18BP levels indicating the recovery from sepsis, and possibly the opportunity of facing a successful SBT, could not be calculated." (PMID 35054259, 2021). "Moreover, in our recent study on a similar cohort of sepsis patients, we showed that the plasma levels of IL-8, IL-18, and IL-33 – three cytokines belonging to the IL-1-family – were significantly higher in early deceased patients compared to day 5+ survivors." (PMID 34966382, 2021). "In accordance with the expected results, we observed a significant increase in the expression levels of pyroptosis-related markers in the liver of CD38-deficient septicemia mice, such as NLRP3, cleaved caspase-1, IL-1β, and IL-18, accompanied by the increase in cleaved caspase-3." (PMID 33860064, 2021). "According to Maher’s findings (2014), the CSTB-deficient mice were significantly more sensitive to the lethal LPS-induced sepsis and could secrete higher amounts of pro-inflammatory cytokines IL-1β and IL-18." (PMID 33926569, 2021). "Several studies have shown that elevated plasma levels of IL-18 have been correlated with unsatisfactory clinical outcome in patients with sepsis and therefore IL-18 may be an important biomarker in the evaluation of septic patients." (PMID 34577795, 2021). "Next, we found that Pellino1 protein could induced the protein expression of Pellino1, TRAF6 and NF-κB and increased the levels of TNF-α, IL-6, IL-1β and IL-18 in mice of sepsis." (PMID 33632252, 2021). "Determination of FGF-2 and IL-18 levels in combination may represent a biomarker for the differential diagnosis of AOSD from sepsis, based on the measurement of multiple cytokines." (PMID 32381117, 2020). "Moreover, neutralization of IL18 has been proposed in heart failure, Fabry cardiomyopathy and sepsis-induced cardiac dysfunction." (PMID 33193300, 2020). "Unlike TNF-α, whose synthesis and secretion are inflammasome-independent, production of IL-1β and IL-18, which requires inflammasome-dependent caspase-1 activation, was more abundant in the serum of Dox-induced iUVRAGFS mice than littermate control in sepsis." (PMID 31831743, 2019). "Deficient autophagy was associated with increased NLRP3 inflammasome assembly and culminated caspase-1 activation as observed in sepsis, enabling enhanced cleavage of pro-IL-1β and pro-IL-18 into their biologically active forms IL-1β and IL-18 in DSS-treated UVRAGFS mice colons." (PMID 31831743, 2019).
Sepsis (continued). "While existing studies show alterations of IL-23, IL-18 and sRAGE in sepsis, with likely biological consequences and potential applicability as diagnostic, prognostic and/or therapeutic targets, these markers have not yet been evaluated in bacterial meningitis." (PMID 29394248, 2018). "IL-18 has also been viewed as a potential therapeutic target in sepsis." (PMID 29394248, 2018). "Increased levels of IL-18 usually occur during endogenous inflammatory processes, such as sepsis." (PMID 30399190, 2018). "High serum level of IL-18 is also observed in sepsis patients." (PMID 30687316, 2018). "In multiple states of disease, such as schizophrenia, sepsis, viral infection, and autoimmunity, elevated IL-18 levels are found with IL-18BP concentrations that have ballooned substantially higher than those found in steady-state ratios with IL-18." (PMID 28900426, 2017). "The IL-18 protein, also known as Interferon-γ inducing factor, has been reported to have pro-inflammatory activity and to play a major role in the development of sepsis." (PMID 26197109, 2015). "In our recent work, we demonstrated that stefin B-deficient mice were significantly more sensitive to the lethal lipopolysaccharide (LPS)-induced sepsis, due to increased caspase-11 expression and secreted higher amounts of pro-inflammatory cytokines IL-1β and IL-18." (PMID 26696823, 2015). "Hence, the caspase-1 function in sepsis was independentof processing and releasing IL-1β and IL-18, in spite of having reducedlevels of serum IL-1β, IL-18 and IL-6 incaspase-1−/− mice during sepsis." (PMID 25412304, 2014). "Inflammasome activation is exclusively responsible for caspase-1-mediated IL-1β and IL-18 maturation and secretion in immune cells, and circulating IL-1β and IL-18 levels are known to be increased in critically ill patients with both sepsis and ARDS." (PMID 24391478, 2013). "Interestingly, patients with septic shock exhibited lower concentrations of two major NK-cell stimulating cytokines, IL-12 (p = 0.035) and IL-18 (p = 0.054) than those with severe sepsis." (PMID 23236375, 2012). "• CD69 expression is enhanced on NK cells from SIRS and sepsis patients but may still be futher increased by the addition of IL-15 plus IL18." (PMID 23098236, 2012). "On the other hand, caspase-1 activation of IL-1β and IL-18 also represents protective host defense mechanisms, and their inactivation may well be an important component of immunoparalysis in sepsis." (PMID 21244670, 2011). "Furthermore, we identified that the plasma levels ratio for miR-150/interleukin-18 can be used for assessing the severity of the sepsis." (PMID 19823581, 2009). "Furthermore, we identified a plasma miRNA ratio (miR-150/IL-18) that can be used for assessing the severity of the sepsis." (PMID 19823581, 2009). "Targeting IL-18 or its genetic variations might offer new avenues for sepsis therapy." (PMID 42311758, 2026). "In addition, the immune response mediator of IL-18 and proinflammatory mediator of IL-1 receptor accessory protein (IL1RAP) were sharply increased in the induced group, which was closely associated with sepsis severity in patients." (PMID 40238755, 2025). "IL-18`s behavior in different sepsis remains complex and may depend on microbial etiology." (PMID 40510342, 2025). "Finally, the broader clinical relevance of IL-18 extends beyond sepsis." (PMID 40510342, 2025). "Similarly, a study on sepsis revealed curcumin's ability to decrease serum inflammatory markers (IL-6, IL-18), oxidative stress indicator MDA, and increase antioxidants like Nrf2, catalase, and SOD, implicating its potential to target ferroptosis-related lipid peroxidation in clinical settings." (PMID 38519984, 2024). "Furthermore, the consequences of CKD, including sepsis, fibrosis, and accelerated vascular calcification, may be influenced by the IL-1β/IL-18 axis." (PMID 38449859, 2024).
Sepsis (continued). "Therefore, the elevation of IL-1β and IL-18 secretion by infected monocytes may contribute, at least in part, to sepsis observed in melioidosis patients." (PMID 39042701, 2024). "In models of sepsis, for example, injection of a low or moderate dose of lipopolysaccharide (LPS) induces a moderate rise in IL-18 levels that enhances anti-bacterial host defenses, while injection with high doses results in sustained, high levels of IL-18, that impair host antibacterial defenses." (PMID 36823262, 2023). "Our group has demonstrated that dual inhibition or deficiency of IL-1 and IL-18 protect against mortality in preclinical models of sepsis and shock, whereas single blocking could not." (PMID 37582864, 2023). "Therefore, the correction between LIGHT/IL-18 levels and PAI-1 levels identified by this study suggests that LIGHT/IL-18 may contribute to ARDS/AHRF in sepsis by increasing the PAI-1 levels." (PMID 35203474, 2022). "In addition, the overexpression of IL‐18 may disrupt the balance of IL‐18 and its inhibitor protein, IL‐18 Binding Protein (IL‐18BP), which may lead to severe diseases such as sepsis and acute kidney injury." (PMID 36495108, 2022). "Indeed IL-18 is a biomarker to differentiate sepsis and septic shock status." (PMID 34489933, 2021). "Last, previous studies had proposed that PCT, IL-18 combined with fibroblast growth factor 2 (FGF 2) and modified Pouchot Score including elevated serum ferritin levels could be a useful diagnostic tool to distinguish AOSD and sepsis." (PMID 33868298, 2021). "Pyroptotic cells release IL-1β and IL-18 and then stimulate and recruit neutrophils and macrophages to the focus of infection, which may be an effect of pyroptosis in the early stage of sepsis." (PMID 34257519, 2021). "Sepsis was independently associated with higher serum IL-18 and TNF levels in two-time-point GEE models (before and at the end of SBT) adjusted for APACHE II score and age, with beta coefficients (95% CI, p values) as follows: IL-18 388 (53—723, p = 0.023), and TNF 32 (0.3—64, p = 0.048)." (PMID 35054259, 2021). "Interestingly, we showed for the first time, that at the time that patients were considered as eligible for SBT, serum IL-18 levels and its relative mRNA expression increased in those recovering from sepsis and were significantly higher as compared to patients admitted for non-septic causes." (PMID 35054259, 2021). "Therefore, a multi-marker approach including u-actin and the measurement of various damage biomarkers (e.g. urine Cystatin C, KIM-1, NGAL, IL-18) may provide valuable information regarding the more accurate staging of sepsis-related AKI." (PMID 34310652, 2021). "Therefore, the effect of IL-18 on PRRs expression and cytokines production could account for the severity of the inflammatory response observed in these diseases, particularly in sepsis." (PMID 25873755, 2015). "Moreover, although MyD88 is also downstream of the IL-1R and IL-18 pathways, neutrophil recruitment 6 h after non-severe sepsis induction was similar between IL-18-deficient mice treated with IL-1Ra and control mice." (PMID 25084278, 2014). "However, we recently showed in a mouse model that purified NK cells are responsive to TLR agonists in the presence of IL-15/IL-18 and that they become tolerant to this ex vivo challenge following polymicrobial sepsis, which is in favor of a deactivation of NK cells themselves." (PMID 23098236, 2012). "Therefore, first we performed target prediction for miR-150 by using miRGen and found that among the predicted targets, at least 20 genes were functionally related to immune system processes; among these was IL-18, which is reportedly increased in patients with sepsis." (PMID 19823581, 2009). "This study underscores the pivotal role of necroptosis in the pathophysiology of sepsis, as reflected by elevated levels of RIPK1, IL-1β, and IL-18 and reduced expression of caspase-8 across both pediatric and adult patients." (PMID 40722817, 2025).